PCSK9 (proprotein convertase subtilisin/kexin type 9)
Diseases named in the same sentence as PCSK9 in open-access papers (continued):
Sharing a sentence is not in itself a finding about the gene and the disease.
hepatoblastoma (1 paper, 2021). Hepatoblastoma (HB) is a malignant hepatic tumor and is the most common pediatric liver cancer. "HepG2 is a hepatoblastoma cell line with relatively low GSTP1 protein expression, indicating that PCSK9 may affect the growth of HepG2 cells through other mechanisms, a possibility to be addressed in our future research." (PMID 33893729, 2021).
hereditary angioedema (1 paper, 2025). Hereditary angioedema (HAE) is a genetic disease characterized by the occurrence of transitory and recurrent subcutaneous and/or submucosal edemas resulting in swelling and/or abdominal pain. "CRISPR/Cas and base editing machinery can already be delivered via lipid nanoparticles to hepatocytes to delete specific genes (e.g., KLKB1 for hereditary angioedema and PCSK9 for familial hypercholesterolaemia), with promising results in clinical trials." (PMID 41562671, 2025).
homozygous familial hypercholesterolemia (1 paper, 2025). "ASOs: antisense oligonucleotides; LDL-C: low-density lipoprotein-cholesterol; HoFH: homozygous familial hypercholesterolemia; ANGPTL3: angiopoietin-like protein 3; PCSK9: proprotein convertase subtilisin/kexin type; LFTs: liver function tests." (PMID 40264627, 2025).
Hypercalcemia (1 paper, 2022). An abnormally increased calcium concentration in the blood. "No study, to our knowledge, has explored circulating PCSK9 level in the context of hypercalcemia." (PMID 35268464, 2022).
Hyperkeratosis (1 paper, 2023). Hyperkeratosis is a histopathological term defining a thickened stratum corneum and may be present in many different skin conditions, with many possible overlaps. "The expression of PCSK9 was demonstrated to be enhanced in lesioned psoriatic skin where it potentiates proliferation of keratinocytes and their hyperkeratosis, parakeratosis and acanthosis, as well as it prevents keratinocytes from apoptosis." (PMID 37763277, 2023).
Infertility (1 paper, 2023). "Further research is required to confirm the association between HMGCR and PCSK9 inhibitors and their impact on menorrhagia and infertility." (PMID 38027179, 2023). "Analysis using exposure data from GLGC found that PCSK9 inhibitor was associated with a higher risk of infertility in patients (IVW: OR [95%CI] = 1.1211 [1.0124, 1.2298], p=3.93× 10−2)." (PMID 38027179, 2023). "PCSK9 inhibitors significantly increased the risk of infertility in patients (OR [95%CI] = 1.14 [1.06, 1.23], p<0.05)." (PMID 38027179, 2023). "Conversely, PCSK9 inhibitors can increase the risk of infertility in patients (OR [95%CI] = 1.14 [1.06, 1.23])." (PMID 38027179, 2023). "Following the drug-targeted MR analysis, our findings suggest that PCSK9 inhibitors are associated with a significant increase in the risk of infertility among patients." (PMID 38027179, 2023). "On the other hand, PCSK9 inhibitors can significantly increase the risk of infertility in patients." (PMID 38027179, 2023). "The findings suggest that PCSK9 inhibitors may significantly increase the risk of infertility in patients." (PMID 38027179, 2023). "However, caution should be exercised when considering the use of PCSK9 inhibitors to lower lipids in female patients who desire to conceive, as it may potentially increase the risk of infertility." (PMID 38027179, 2023). "Our research findings indicate that PCSK9 inhibitors may pose a risk for infertility patients." (PMID 38027179, 2023). "Through a large-scale MR analysis of female reproductive endocrine diseases using data from a Finnish database, we investigated the effects of three common drug targets (HMGCR, PCSK9, and NPC1L1) on various conditions including PCOS, POF, PMS, menorrhagia, oligomenorrhea, and infertility." (PMID 38027179, 2023).
intestinal tumors (1 paper, 2022). "Our previous in vivo study also revealed that PCSK9 expression was able to promote growth and malignant transformation of intestinal tumors in mice with Apc mutation." (PMID 36242053, 2022).
irritable bowel syndrome (1 paper, 2022). Irritable bowel syndrome (IBS) is a chronic functional condition of the lower gastrointestinal (GI) tract characterized by abdominal pain or discomfort and disordered bowel habit (diarrhea, constipation, or fluctuation between the two). "Additionally, this altered microbiome can affect TMAO through an increase in Proteobacteria and other TMA producers, and PCSK9 through conditions such as small intestinal bacterial overgrowth (SIBO) or irritable bowel syndrome (IBS), which are both correlated with increased PCSK9 production." (PMID 36557234, 2022).
ischemic cardiomyopathy (1 paper, 2024). Ischemic cardiomyopathy is a cardiomyopathy in which a weakness in the muscle of the heart due to inadequate oxygen delivery to the myocardium with coronary artery disease being the most common cause. "Upon conducting an online analysis of the single-cell sequencing results, we identified restricted PCSK9 expression within human cardiac cells, which was observed in both ischemic cardiomyopathy (ICM) at end-stage HF and non-failing (NF) controls." (PMID 38383373, 2024). "To assess the expression of PCSK9 in cardiac cells within the context of ischemic heart failure (HF), we analyzed PCSK9 protein expression in end-stage ischemic cardiomyopathy (ICM) and compared it to non-failing (NF) controls using the Single Cell Portal." (PMID 38383373, 2024).
Kawasaki disease (1 paper, 2024). A rare inflammatory disease characterized by an acute febrile, systemic, self-limiting, medium-vessel vasculitis primarily affecting children. "Plasma concentrations of ARG1, CCL20, CD163, CORIN, CXCL9, PCSK9 and ADAMTS2 were quantified in MIS-C (n = 22), Kawasaki disease (n = 23), definite bacterial (n = 28) and viral (n = 27) disease and healthy controls (n = 8)." (PMID 38359342, 2024).
kidney injury (1 paper, 2025). Trauma to the kidney. "PCSK9 inhibitors are a new lipid-lowering agent which may be a novel treatment option for patients with CCE-induced kidney injury." (PMID 41209160, 2025).
knee osteoarthritis (1 paper, 2024). "PCSK9-mediated LDL cholesterol also demonstrated an association with OA of the hip or knee (OR = 0.915, 95%CI: 0.847 to 0.988, p = 0.023, q = 0.07) and knee osteoarthritis (OR = 0.901, 95%CI: 0.821 to 0.990, p = 0.03, q = 0.07)." (PMID 38416763, 2024). "PCSK9-mediated LDL cholesterol, targeted by drugs such as evolocumab and alirocumab, also showed a suggestive relationship with OA of the hip or knee (OR = 0.915, 95%CI: 0.847 to 0.988, p = 0.023, q = 0.07) and knee osteoarthritis (OR = 0.901, 95%CI: 0.821 to 0.990, p = 0.03, q = 0.07)." (PMID 38416763, 2024).
Left ventricular dilatation (1 paper, 2023). Enlargement of the chamber of the left heart ventricle. "Mice with cardiomyocyte-specific deletion of Pcsk9 had reduced contractile capacity, impaired cardiac function, and left ventricular dilatation at 28 weeks of age and died prematurely." (PMID 36880401, 2023).
leukocytoclastic vasculitis (1 paper, 2021). "Mipomersen, is not, however, associated with some adverse effects of PCSK9 inhibitors including hypersensitivity reaction and rare occurrence of leukocytoclastic vasculitis." (PMID 34357325, 2021).
male infertility (1 paper, 2024). The inability of the male to effect fertilization of an ovum after a specified period of unprotected intercourse. "In addition, the results also found that PCSK9 inhibitors increased the risk of PH, and NPC1L1, HMGCR inhibitors decreased the risk of PCa, but at the same time HMGCR inhibitors increased the risk of male infertility." (PMID 38390206, 2024).
Menorrhagia (1 paper, 2023). Prolonged and excessive menses at regular intervals in excess of 80 mL or lasting longer than 7 days. "Our findings also suggest that HMGCR inhibitors, but not PCSK9 or NPC1L1 inhibitors, have a protective effect on patients with menorrhagia." (PMID 38027179, 2023).
mesothelioma (1 paper, 2024). A usually malignant and aggressive neoplasm of the mesothelium which is often associated with exposure to asbestos. "In BLCA (P < 0.01), KIRP (P < 0.001), STAD (P < 0.01), and THCA (P < 0.001), the expression level of PCSK9 was enriched in the T3&T4 subgroup than in the T1&T2 subgroup, while the opposite result was identified in mesothelioma (MESO) (P < 0.05)." (PMID 38600469, 2024).
morbid obesity (1 paper, 2020). An excess of body weight, normally defined as an individual with a body mass index greater than 35 or a body weight greater than one hundred percent of ideal body weight. "A relationship between zonulin and PCSK9 levels after fat load in individuals with morbid obesity may exist." (PMID 32403394, 2020).
myopia (1 paper, 2019).
nutrition disorders (1 paper, 2022). "Compared with statins/ezetimibe, PCSK9 inhibitors exhibited a lower reporting probability of adverse events associated with “nervous system disorders”, “psychiatric disorders” and “metabolism and nutrition disorders”, but mixed results for musculoskeletal disorders." (PMID 36506552, 2022). "Compared with statins/ezetimibe, PCSK9 inhibitors exhibited lower ROR values for adverse events associated with SOC “nervous system disorders”, “psychiatric disorders” and “metabolism and nutrition disorders” (all RORs < 1), but mixed results for musculoskeletal disorders." (PMID 36506552, 2022).
opioid use disorder (1 paper, 2022). A substance-related disorder that involves the recurring use of opioids despite negative consequences. "The PCSK9 locus has only recently been implicated in GWAS, specifically in gene-based analyses of opioid use disorder." (PMID 36580462, 2022).
oropharyngeal cancer (1 paper, 2021). Carcinoma, predominantly squamous cell, arising from the epithelial cells of the oropharynx.
osteonecrosis (1 paper, 2025). A none disease characterized by death of bone tissue due to a lack of blood supply.
ovarian dysfunction (1 paper, 2023). The inability of the ovaries to function. "Among the genes we identified through coexpression of three datasets, PNPLA3, MVD, MMP9, oncostatin M (OSM), LCK, triggering receptor expressed on myeloid cells 1 (TREM1), FADS2, proprotein convertase subtilisin/kexin type 9 (PCSK9), and C3 are involved in lipid metabolism and ovarian dysfunction." (PMID 37537636, 2023).
ovarian epithelial tumor (1 paper, 2023). A benign, borderline, or malignant tumor that originates from the surface epithelium of the ovary. "Notably, patients with ovarian epithelial tumors had the highest frequency of PCSK9 genetic alterations (5%), including amplification of copy numbers and deep deletions." (PMID 37860186, 2023).
overnutrition (1 paper, 2023). An imbalanced nutritional status resulting from excessive intake of nutrients. "Therefore, overnutrition may lead to higher PCSK9 protein levels, which might lead to increased LDL-C." (PMID 37012310, 2023).
pancreatic neuroendocrine tumor (1 paper, 2020). Pancreatic endocrine tumor, also known as pancreatic neuroendocrine tumor (PNET), describes a group of endocrine tumors originating in the pancreas that are usually indolent and benign, but may have the potential to be malignant. "In BON-1 cells, a frequently used model system of pancreatic neuroendocrine tumor (PNET) research, silencing PCSK9 expression by either agomirs of miR-224 or by siRNA directed against PCSK9 increased the rate of apoptosis." (PMID 33364976, 2020).
paraganglioma (1 paper, 2024). A benign or malignant neoplasm arising from paraganglia located along the sympathetic or parasympathetic nerves. "PCSK9 expression was positively correlated with immune score, stomal score, and ESTIMATE score in BLCA (P < 0.001), BRCA (P < 0.001), pheochromocytoma and paraganglioma (PCPG) (P < 0.001) and THCA(P < 0.001)." (PMID 38600469, 2024).
periodontal disease (1 paper, 2012). "Although oral infection can mimic human periodontal disease, and it is clear that oral infection with P. gingivalis does, in fact, affect Pcsk9 gene expression in the liver (data not shown), subsequent change in lipid metabolism can be easily observed in peritoneal infection model." (PMID 22992388, 2012).
psoriasis vulgaris (1 paper, 2023). Plaque psoriasis is the most common presentation of psoriasis. "The aim of this study was to analyze the influence of cyclosporine treatment on the NGAL and PCSK9 levels in patients with psoriasis vulgaris." (PMID 37763277, 2023). "The aim of the study was to analyze the influence of cyclosporine therapy on serum levels of NGAL and PCSK9 in patients with psoriasis vulgaris." (PMID 37763277, 2023).
psoriatic arthritis (1 paper, 2024). Joint inflammation associated with psoriasis. "Our study elucidates that genetically proxied PCSK9 inhibition is inversely associated with psoriatic arthritis susceptibility, underscoring the therapeutic potential of extant PCSK9 inhibitors." (PMID 38341813, 2024). "A significant association was observed between genetically represented proprotein convertase subtilisin/kexin type 9 (PCSK9) inhibition and a decreased risk of psoriatic arthritis (odds ratio [OR]: 0.51; 95% CI 0.14–0.88; P < 0.01)." (PMID 38341813, 2024). "Inhibition of PCSK9 is associated with reduced psoriatic arthritis risk, highlighting the potential therapeutic benefits of existing PCSK9 inhibitors." (PMID 38341813, 2024). "This Mendelian randomization analysis underscores the pivotal role of PCSK9 in the etiology of psoriatic arthritis." (PMID 38341813, 2024).
respiratory failure (1 paper, 2018). The significant impairment of gas exchange within the lungs resulting in hypoxia, hypercarbia, or both, to the extent that organ tissue perfusion is severely compromised. "Furthermore, patients with respiratory failure or septic shock had increased PCSK9 levels compared to septic patients without these complications." (PMID 30002483, 2018).
Respiratory tract infection (1 paper, 2024). An infection of the upper or lower respiratory tract. "Pharmacovigilance studies may be required to monitor patients treated with therapeutic PCSK9 inhibitors for exacerbations of respiratory diseases or respiratory tract infections." (PMID 38198221, 2024).
retinal diseases (1 paper, 2024). "Therefore, in addition to lipid-lowering effects, the use of PCSK9 inhibitors may potentially contribute to the reduction of retinal diseases in diabetic patients." (PMID 38757060, 2024).
rhinitis (1 paper, 2021). An inflammation of the mucous membrane lining the nose, usually associated with nasal discharge. "Since the documented symptoms stated by the patients were mainly unspecific (e.g. joint or muscle pain, rhinitis), it remains speculative whether they were associated with PCSK9 inhibitor therapy." (PMID 33894772, 2021).
sarcoma (1 paper, 2024). A usually aggressive malignant neoplasm of the soft tissue or bone. "In addition, PCSK9 expression was positively correlated with only stomal score or ESTIMATE score in DLBC (P < 0.05), KIRC (P < 0.05), sarcoma (SARC) (P < 0.01), and uveal melanoma (UVM) (P < 0.05)." (PMID 38600469, 2024).
skin rashes (1 paper, 2025). "Seven patients (2.7%), including four men and three women, switched from PCSK9 inhibitors to inclisiran: three (1.1%) due to adverse effects (flu-like symptoms and skin rashes) and four (1.6%) due to low adherence." (PMID 40648843, 2025).
Sleep apnea (1 paper, 2024). An intermittent cessation of airflow at the mouth and nose during sleep is known as sleep apnea. "The use of HMGCR lipid-lowering drugs (such as statins) and PCSK9 inhibitors has a protective effect against sleep apnea." (PMID 39470521, 2024). "According to our DMR analysis, HMGCR and PCSK9, which act by lowering serum LDL-C levels, were inversely associated with the risk of sleep apnea syndrome (OR = 0.627; 95% CI = 0.511–0.767; P = 6.30E−06) (OR = 0.775; 95% CI = 0.677–0.888; P = .0002)." (PMID 39470521, 2024). "The DMR results suggested that the use of HMGCR lipid-lowering drugs (such as statins) and PCSK9 inhibitors has a protective effect against sleep apnea syndrome." (PMID 39470521, 2024). "Our DMR results suggest that HMGCR lipid-lowering drugs such as statins and PCSK9 inhibitors have a protective effect against sleep apnea syndrome." (PMID 39470521, 2024). "However, the mechanism of action of HMGCR lipid-lowering drugs and PCSK9 inhibitors in sleep apnea syndrome requires further investigation." (PMID 39470521, 2024). "Taken together, these findings and the results of the TSMR analysis suggest that the protective effect of HMGCR lipid-lowering drugs and PCSK9 inhibitors on sleep apnea syndrome may not be related to a reduction in the serum LDL-C concentration." (PMID 39470521, 2024).
spina bifida (1 paper, 2015). A congenital neural tube defect in which vertebrae are not fully formed. "Compared with normal fetuses, the reduced expression of PCSK9 protein in spina bifida was along the defective regions of spina bifida." (PMID 26691006, 2015).
testicular germ cell tumor (1 paper, 2024). A germ cell tumor arising from the testis. "The results showed that in BLCA (P < 0.001), BRCA (P < 0.001), COAD (P < 0.05), and THCA (P < 0.001), PCSK9 was positively correlated with PDCD1, CD274, and CTLA4 but negatively correlated in HNSC (P < 0.05) and testicular germ cell tumor (TGCT) (P < 0.01)." (PMID 38600469, 2024).
thymoma (1 paper, 2024). A neoplasm arising from the epithelial cells of the thymus. "According to the PFI analysis, high PCSK9 expression was correlated with poor prognoses in BLCA (P = 0.001), KIRC (P = 0.009), and thymoma (THYM) (P = 0.013) patients." (PMID 38600469, 2024).
urinary stones (1 paper, 2023). "We used urinary stones as an exposure factor, circulating lipids and lipid-lowering drugs as outcome factors(We did not extract SNPs associated with exposure factors in the GWAS for HMGCR inhibitors and PCSK9 inhibitors)." (PMID 38107516, 2023).